PIP4P2 (phosphatidylinositol-4,5-bisphosphate 4-phosphatase 2)
Description:
Catalyzes the hydrolysis of phosphatidylinositol-4,5-bisphosphate (PtdIns-4,5-P2) to phosphatidylinositol-4-phosphate (PtdIns-4-P). Does not hydrolyze phosphatidylinositol 3,4,5-trisphosphate, phosphatidylinositol 3,4-bisphosphate, inositol 3,5-bisphosphate, inositol 3,4-bisphosphate, phosphatidylinositol 5-monophosphate, phosphatidylinositol 4-monophosphate and phosphatidylinositol 3-monophosphate. Negatively regulates the phagocytosis of large particles by reducing phagosomal phosphatidylinositol 4,5-bisphosphate accumulation during cup formation (By similarity).
Synonyms: TMEM55A; DKFZp762O076
Tractability: Antibody: UniProt places it where antibodies can reach, with medium confidence; UniProt predicts a signal peptide or a membrane-spanning region; its Gene Ontology location is reachable by antibodies, with medium confidence. PROTAC: ubiquitination databases record sites on it.
Gene: Protein-coding gene on chromosome 8 (90,990,482 to 91,041,007, reverse strand). Ensembl gene ENSG00000155099.
Subcellular location: Late endosome membrane; Lysosome membrane; Cytoplasmic vesicle, phagosome membrane; Cell membrane
Gene Ontology:
Molecular function: phosphatidylinositol-4,5-bisphosphate 4-phosphatase activity; protein binding
Biological process: phosphatidylinositol dephosphorylation; negative regulation of phagocytosis
Cellular component: late endosome membrane; lysosomal membrane; phagocytic vesicle membrane; plasma membrane
Genetic constraint (gnomAD): Loss-of-function variants: 17 observed, 30.81 expected, observed/expected ratio (o/e) 0.55, 90% interval 0.38 to 0.83. The upper end of that interval is the gene's LOEUF score, 0.83, which puts it in group 3 of 6, group 1 being the genes least tolerant of losing a copy. Missense variants: 257 observed, 317.75 expected, observed/expected ratio (o/e) 0.81, 90% interval 0.73 to 0.9. Synonymous variants: 104 observed, 111.12 expected, observed/expected ratio (o/e) 0.94, 90% interval 0.8 to 1.1.
Homologues: Orthologues: chimpanzee PIP4P2 (100% identical), macaque PIP4P2 (99% identical), pig PIP4P2 (98% identical), dog PIP4P2 (97% identical), mouse Pip4p2 (96% identical), rat Pip4p2 (96% identical), guinea pig PIP4P2 (96% identical), tropical clawed frog pip4p2 (90% identical), zebrafish pip4p2 (90% identical), Drosophila melanogaster CG6707 (44% identical), Caenorhabditis elegans pipp-4P (39% identical), Caenorhabditis elegans F52E1.9 (19% identical). Paralogues in human: PIP4P1 (56% identical).